NUP98 (nucleoporin 98 and 96 precursor)
Diseases named in the same sentence as NUP98 in open-access papers (continued):
Sharing a sentence is not in itself a finding about the gene and the disease.
leukemia (continued). "The mechanisms behind Nup98-based leukemias have converged on the chromatin-binding function of Nup98." (PMID 31717499, 2019). "Leukemogenic NUP98 fusion proteins have been extensively studied and NUP98-related leukemia has been addressed in several review articles in recent years." (PMID 30669574, 2019). "Both MLL-based and Nup98-based leukemias are associated with pathogenic upregulation of Hox genes, supporting the notion that both MLL and Nup98 normally regulate expression of Hox genes." (PMID 31717499, 2019). "In this study, we aimed to determine how Nup98 activates gene expression in mammalian HPCs in order to understand how Nup98 translocation mutants trigger leukemia." (PMID 29269482, 2017). "The fact that many Nup98 fusion-mediated leukemias appear to be triggered by activation of the HOXA and HOXB loci and Meis1 strongly suggests that the recruitment of the N-terminal portion of Nup98 fusions (through Nup98 itself) is a critical step." (PMID 29269482, 2017). "In the future, we hope to compare H3K4me3 and gene expression in cells from patients expressing different Nup98 translocations to characterize how disruption of H3K4me3 specifically promotes the onset of leukemia in vivo." (PMID 29269482, 2017). "In leukemia, Nup98 is frequently found in the form of Nup98-fusions, which consist of N-terminal half of Nup98 containing multiple phenylalanine-glycine (FG) repeats and C-terminus of various partner proteins." (PMID 26740045, 2016). "In these leukaemias, the intrinsically disordered region of the nuclear pore protein NUP98 is fused to domains of various nuclear proteins that are often involved in chromatin modification and transcriptional control, for example, HOXA9, DDX10, NSD1 and KDM5A53,54." (PMID 40468084, 2025). "Moreover, NUP98 fusions co-occur with additional mutations, including FLT3-internal tandem duplication, which drives increased proliferation and further promotes leukemia development and progression." (PMID 40264981, 2025). "NUP98 gene is recurrently translocated, particularly in pediatric leukemia cases." (PMID 39551864, 2024). "Menin inhibitors have demonstrated efficacy in preclinical models of leukemia with NUP98 fusion." (PMID 39179671, 2024). "Rearrangements in KMT2A, NUP98 and mutated NPM1 are considered potent drivers of leukemia but may be accompanied by activation of other oncogenic pathways of both prognostic and therapeutic relevance." (PMID 38174649, 2023). "In summary, ABL1 loss may serve as important diagnostic factor predicting more malignant phenotype of AML1-ETO and NUP98-fusions -positive leukemias as well as their unique pharmaceutical vulnerabilities to PI3K, ATR and DNA-PK inhibition." (PMID 36959186, 2023). "Additionally, administration of VTP50469 resulted in improved survival outcomes in mice with NUP98-rearranged leukemias 29, highlighting the potential of VTP50469 as a targeted agent for the treatment of patients with NUP98-rearranged leukemias." (PMID 37705755, 2023). "The role of NUP98 in leukemia development depends on its interaction with the PHD3 domain in KDM5A." (PMID 37325571, 2023). "Although NUP98-fusion proteins in leukemia have been linked to HDAC binding, in addition to many other transcription regulators including p300, it remained incompletely understood regarding how HDAC influences NUP98 function." (PMID 37353594, 2023). "Importantly, Menin inhibition completely blocked disease progression by eradicating leukemic blasts in a patient-derived NUP98::NSD1/FLT3-ITD-positive PDX model, suggesting that the NUP98 fusion drives the leukemia." (PMID 37520776, 2023). "Intriguingly, this upregulation of HOX genes is shared with NUP98::NSD1, DEK (DEK proto-oncogene)::NUP214 (nucleoporin 214), and NPM1 (nucleophosmin 1) mutated cases, suggesting HOXA and HOXB overexpression is a common alteration in leukemia development." (PMID 37325571, 2023). "NUP98 fusion oncoprotein is a driver of childhood leukaemia." (PMID 37980165, 2023).
leukemia (continued). "On the other hand, ABL1 kinase could become a therapeutic target since imatinib increased the sensitivity of AML1-ETO and NUP98-fusions -positive leukemias to PI3K, ATR and DNA-PK inhibitors." (PMID 36959186, 2023). "Given that inhibiting binding of Crm1 to NES cargo also impairs the interaction of Crm1 with NUP98 fusion proteins, SINEs could likewise be of therapeutic utility in the context of NUP98 fusion leukemias, which respond poorly to existing therapies." (PMID 32343715, 2020). "However, one of the common features of both Nup98 and Nup214-fusion–expressing leukemia is aberrant activation of HOX genes." (PMID 31755865, 2019). "Importantly, the NUP98 translocations that occur in AML all share the N-terminus of the protein and are thought to initially lead to epigenetic dysregulation of different leukemia-associated genes including HOXA7, HOXA9, and HOXA10 in myeloid precursor cells." (PMID 31467532, 2019). "The mechanism of Nup98 translocation-mediated leukemias is poorly understood." (PMID 29269482, 2017). "Do all Nup98-mediated leukemias proceed through a common mechanism?" (PMID 29269482, 2017). "A key question in the field is whether all Nup98 fusion proteins promote leukemia via the same mechanism or whether the identity of the C-terminal-binding partner determines which genes become misregulated." (PMID 29269482, 2017). "Importantly, such aberrations were not only observed in transiently transfected HeLa cells but also in mouse bone marrow cells immortalized by Nup98 fusions and in cells derived from leukemia patients harboring Nup98 fusions." (PMID 27031510, 2016). "Collectively these data indicate that the aberrant NE phenotype observed in transfected HeLa cells is also found in murine bone marrow cells immortalized by Nup98 fusions as well as in primary tumor cells from leukemia patients carrying translocations leading to Nup98 fusions." (PMID 27031510, 2016). "The role of LAP2α in Nup98-associated leukemia is likely independent of lamin A/C as mouse bone marrow cells and patient-derived bone marrow cells show alterations in LAP2α in a manner independent of lamin A/C expression." (PMID 27031510, 2016). "In addition, in a mouse leukemia model generated by transplant of Bcr/Abl- and NUP98/HOXA9-transduced hematopoietic progenitor cells into sub-lethally irradiated recipients, CTLs recognizing antigens expressed in leukemia cells were exhausted." (PMID 26658107, 2015). "Hoxb4, a 3′-located Hox gene, enhances hematopoietic stem cell (HSC) activity, while a subset of 5′-located Hox genes is involved in hematopoiesis and leukemogenesis, and some of them are common translocation partners for Nucleoporin 98 (Nup98) in patients with leukemia." (PMID 23326393, 2013). "Finally, the involvement of NUP98 in developmental regulation sheds light on its involvement in multiple types of leukemia where it is fused to various transcription regulators." (PMID 23468646, 2013). "NURD displays homology to the protein SP100, a component of the promyelocytic leukemia-associated nuclear body, implying that NUP98 might be involved in the regulation of nuclear bodies and is consistent with the reported link of NUP98 to leukemia." (PMID 23468646, 2013). "Additional binding specificity and stability is in part achieved through interaction with other homeodomain-containing proteins from the multimember PBX or MEIS1 families and co-transduction of MEIS1 with Hox and NUP98-Hox genes also strongly accelerate the onset of leukemia in mice." (PMID 17712416, 2007).
leukemia (continued). "A notable example is the LLPS between nucleoporin 98 (NUP98) of the nuclear pore complex (NPC) and homeobox protein A9 (HOXA9), which contributes to the formation of extensive super‐enhancer (SE)‐like binding patterns, thereby promoting the transcriptional activation of leukemia‐causing genes." (PMID 41319208, 2025). "However, NUP98:NSD1 fusions occur frequently in pediatric AML and are associated with poor prognosis, an NUP98:ASH1L fusion was recently identified by optical gene mapping in secondary AML, and ASH1L also appears to play a role in leukemia driven by MLL1:AF9 fusion." (PMID 39403928, 2024). "In addition, some other leukemias overexpressing HOX and MEIS1 genes might respond to menin inhibition such as leukemias with rearrangement of the nucleoporin 98 gene (NUP98)." (PMID 38651453, 2024). "In addition to its established oncogenic roles in MLLr and NPM1 mutant leukemias, menin may also play a role in NUP98 fusion and UBTF tandem duplication (UBTF-TD) acute leukemias." (PMID 39336822, 2024). "The physical interaction of NUP98 fusion proteins with MLL complexes at promoters in combination with the similar leukemia-associated gene signature in NUP98-r, NPM1-mut, and MLL-r AML raises the question whether NUP98-r AML is dependent on the Menin–MLL interaction." (PMID 37520776, 2023). "Furthermore, the blockade of the menin-MLL1 interaction by the menin-MLL1 inhibitor VTP50469 hampers the chromatin binding of not only menin and MLL1 but also NUP98 fusion proteins, and it also inhibits leukemogenesis in models of NUP98-rearranged leukemias, including NUP98–KDM5A." (PMID 35805040, 2022). "More recently, the binding of NUP98 fusion proteins to HOXA genes was shown to be mediated by the NUP98 moiety through its interaction with proteins of the NSL/MLL1 complexes; this suggests that NUP98 and MLL fusion proteins might use a common pathogenic mechanism to induce leukemias." (PMID 32343715, 2020). "Indeed, the ectopic expression of Nup98-HoxA9 induces leukemia in mice." (PMID 26740045, 2016). "The NUP98 gene also was known to be fused to at least 28 different partner genes in patients with hematopoietic malignancies, including acute myeloid leukemia, chronic myeloid leukemia in blast crisis, myelodysplastic syndrome, acute lymphoblastic leukemia, and bilineage/biphenotypic leukemia." (PMID 24674592, 2014). "For instance, NUP98 fusion oncoproteins, including NUP98-HOXA9, drive leukemia by forming nuclear puncta through liquid-liquid phase separation, involving both homotypic and heterotypic interactions." (PMID 40442783, 2025). "In mouse models, the combination of NUP98 fusion and FLT3-ITD alterations leads to a more aggressive form of leukemia with a shorter latency period." (PMID 39068406, 2024). "Since our initial analysis detected ABL1 deletions in leukemias carrying AML1-ETO and NUP98 translocations, we investigated the role of ABL1 in these leukemias." (PMID 36959186, 2023). "HBO1-MLL interaction inhibitors would complement the therapeutic effects of the emerging MENIN-MLL interaction inhibitors to treat malignant leukemia with subsets of MLL and NUP98 fusions." (PMID 34431785, 2021). "The NUP98 and NUP214 nucleoporins (NUPs) are recurrently fused to heterologous proteins in leukemia." (PMID 32343715, 2020). "It has been shown that some NUPs including NUP88, NUP98 and NUP214 make mechanistic contributions to carcinogenesis, particularly in leukemias." (PMID 29861858, 2018). "HoxA9 overexpression is a feature of leukemia with MLL rearrangements, trisomy 8 and the t(7:11)(p15:p15) translocation that fuses the homeodomain of HoxA9 to Nup98." (PMID 24177192, 2013). "This NUP98::KDM5A-driven model is fully dependent on sustained expression of the oncogenic driver, as its degradation leads to cell cycle arrest, differentiation, and apoptosis of leukemia cells." (PMID 40389480, 2025).
leukemia (continued). "In addition to its central role in MLLr and NPM1c leukemias, MLL1 also plays a role in leukemias driven by chromosomal rearrangement affecting the nucleoporin protein NUP98." (PMID 39403928, 2024). "Our findings may be of particular relevance in the search for new druggable targets, such as the MAPK and ER pathways, that might be explored in the development of specific therapies for NUP98 and NUP214 leukemia." (PMID 32664447, 2020). "NUP98- and NUP214-related leukemia are associated with poor overall survival, and no specific or targeted therapies are as yet available to improve prognosis." (PMID 32664447, 2020). "Lacking established human leukemia cell lines expressing Nup98 fusions we first immortalized mouse bone marrow (BM) cells by retroviral expression of untagged Nup98-HOXA9 and Nup98-HHEX." (PMID 27031510, 2016). "Nup98-HoxA9 also does not require an intact Pbc-interaction motif to promote immortalization or leukemia." (PMID 24177192, 2013). "The involvement of homeobox genes as partners of NUP98 is of particular interest given the growing evidence linking Hox genes, particularly members of the 5′-located members of the HOXA cluster, such as HOXA9, to leukemia." (PMID 17712416, 2007). "Even though global patterns of chromatin accessibility are similar in adult versus childhood leukemia we found genomic regions that were selectively accessible in NUP98-rearranged AML but not in healthy hematopoietic progenitors and other subtypes of pediatric AML." (PMID 40389480, 2025). "Previous studies have shown that the fusion of NUP98 and DDX10 may lead to leukaemia." (PMID 35109823, 2022). "Notably, mutations in epigenetic regulators commonly found in AML were absent, suggesting that the NUP98 fusion proteins themselves may initiate leukemia through epigenetic mechanisms, particularly via changes in histone methylation and acetylation." (PMID 41155189, 2025). "It seems that NUP98-HOX fusions have the ability to initiate and maintain a state of self-renewal necessary, but not sufficient, for the development of leukemia." (PMID 23332017, 2013). "The NUP98-MLL fusion protein expressed in leukemia patients does not retain the structures responsible for interaction with MENIN and LEDGF, suggesting that the MLL portion in NUP98-MLL confers its targeting ability in a MENIN-independent manner." (PMID 34431785, 2021). "Both patients with only the NUP98::TNRC18 fusion and no other fusion genes progressed rapidly and eventually died, indicating that the NUP98::TNRC18 fusion may play a key role in the occurrence and development of leukemia." (PMID 40264981, 2025).
acute myeloid leukemia (71 papers, 2007 to 2026). Acute myeloid leukemia (AML) is a group of neoplasms arising from precursor cells committed to the myeloid cell-line differentiation. "One such dynamic Nup, called Nup98, has been implicated in gene activation in healthy cells and has been shown to drive leukemogenesis when mutated in patients with acute myeloid leukemia (AML)." (PMID 29269482, 2017). "Understanding how Nup98 regulates expression of target genes remains an extremely relevant question, as many patients suffering from acute myeloid leukemia (AML) harbor mutations in which the N terminus of Nup98 is translocated with the C terminus of one of ∼30 different translocation partners." (PMID 29269482, 2017). "The chimera protein NUP98/HOXC13 has a pathogenic importance in acute myeloid leukemia (AML), which leads to the deletion of the mutual fusion of the gene." (PMID 31137568, 2019). "The NUP98 gene is a frequent target for chromosomal translocations, which fuse the N-terminal FG domain of Nup98 to the C-terminal domain of more than 30 different partners and are primarily causing acute myeloid leukemia (AML)." (PMID 26540075, 2015). "Studies indicate that its fusion with the nucleoporin gene NUP98 can induce acute myeloid leukemia (AML)." (PMID 41268576, 2025). "HOXD13 is known to contribute to the pathogenesis of acute myeloid leukemia (AML) through the formation of a fusion protein with NUP98." (PMID 39977830, 2025). "NUP98 chimeric proteins originating from genomic rearrangements are rare recurrent alterations in pediatric acute myeloid leukemia with adverse outcomes." (PMID 39273335, 2024). "Recurrent rearrangements of the NUP98 gene on chromosome 11p15 have been identified in various hematologic neoplasms, including acute myeloid leukemia (AML), myelodysplastic syndromes (MDS), and T-cell acute lymphoblastic leukemia (T-ALL)." (PMID 39301554, 2024). "Chromosomal translocations involving the NUP98 locus are among the most prevalent rearrangements in pediatric acute myeloid leukemia (AML)." (PMID 37520776, 2023). "Here, a previously unrecognized NUP98::ASH1L fusion was detected in a patient with acute myeloid leukemia with prior myelodysplastic/myeloproliferative neoplasia using a genome-wide approach through optical genome mapping." (PMID 37296904, 2023). "The formation of chimeric protein involving NUP98 and transcription factors, such as homeodomain (HD), were observed to induce morphological alterations of the NE in acute myeloid leukemia (AML) cells." (PMID 36899842, 2023). "Previous studies have reported that NUP98 fused with PHF23 to form NP23, which plays an important role in acute myeloid leukemia and is closely associated with disease onset and evolution." (PMID 37626047, 2023). "Recent studies have discovered that nucleoporin-98 and -96 precursor (NUP98)-associated TF chimeras, which are recurrently detected in pediatric acute myeloid leukemia (AML), form nuclear condensates and induce aberrant chromatin looping and leukemogenic gene expression programs." (PMID 36263200, 2022). "Nup98 is involved in at least 14 translocations, mainly associated with hematological malignancies including myelodysplastic syndrome (MDS), acute myelogenous leukemia (AML), and chronic myelogenous leukemia (CML)." (PMID 33375634, 2020). "In this work, we have identified a novel NUP98‐LEDGF rearrangement in acute myeloid leukemia (AML‐M2)." (PMID 30848074, 2019). "The oncogenicity of several Nup98 fusions has been demonstrated in mouse models where Nup98 fusions lead to acute myeloid leukemia recapitulating the human disease phenotype." (PMID 28221134, 2017). "NUP98 is also involved in chromosomal translocations (involving ~30 different genes) in a subset of acute myeloid leukemia patients." (PMID 28345611, 2017). "Chromosomal translocations of the nucleoporin NUP98 have been described in several hematopoietic malignancies, in particular de novo and therapy-related acute myeloid leukemia (AML)." (PMID 27031510, 2016).